BRCA1 (BRCA1 DNA repair associated)
Diseases named in the same sentence as BRCA1 in open-access papers (continued):
Sharing a sentence is not in itself a finding about the gene and the disease.
breast cancer (continued). "Mutations in the BRCA1/BRCA2 genes account for varying proportions of breast cancer families studied, and demonstrate considerable variation in mutational spectra coincident with ethnic and geographical diversity." (PMID 9836472, 1998). "Of 268 Ashkenazi Jewish women with sporadic breast cancer, tested in an unrelated study, 16 carried either the 185delAG mutation of BRCA1 or the 6174delT mutation of BRCA2." (PMID 9743298, 1998). "Our study reveals why BRCA1 deficiency is prone to result in tumorigenesis in LPs and elucidates the key role of replication stress and ELF3 during this process, suggesting that ELF3 could be a promising target for BRCA1-associated breast cancers." (PMID 41498327, 2026). "In addition to the tissue specificity of tumors caused by BRCA1 deficiency, breast cancers associated with BRCA1 deficiency exhibit a set of other distinctive features." (PMID 41498327, 2026). "Second, the higher replication stress levels in LPs may lead to altered expression or modifications of molecules other than ELF3, affecting the development and progression of BRCA1-associated breast cancer, which also needs to be further explored." (PMID 41498327, 2026). "BRCA1-associated breast cancers comprise samples with BRCA1 mutations, heterozygous loss, and homozygous deletion (Mann–Whitney U test) (TCGA: BRCA1-associated, N=362; BRCA1-non-associated, N=720; METABRIC: BRCA1-associated, N=540, BRCA1-non-associated, N=1364)." (PMID 41498327, 2026). "Although many earlier studies did not demonstrate an overall survival benefit, a recently presented study at the San Antonio Breast Cancer Symposium reported a survival advantage associated with RRM in younger women (≤ 40 years) with breast cancer who carry a BRCA1/2 P/LP variant." (PMID 41488281, 2026). "Breast cancer (BC) risk is significantly associated with pathogenic variants in at least eight susceptibility genes: BRCA1 (MIM#113705), BRCA2 (MIM#600185), PALB2 (MIM#610355), ATM (MIM#607585), CHEK2 (MIM# 604373), BARD1 (MIM#601593), RAD51C (MIM#602774), and RAD51D (MIM#602954)." (PMID 41230741, 2026). "Germline BRCA1/2 pathogenic variant (PV) carriers have elevated young-onset breast cancer risk." (PMID 42048167, 2026). "Risk factors for breast cancer include age, family history, inherited gene mutations (such as BRCA1 and BRCA2), hormonal factors (early puberty, late menopause, hormone replacement therapy), obesity, alcohol consumption, and exposure to endocrine‐disrupting chemicals such as BPA." (PMID 41201099, 2026). "Additionally, TNBCs have higher ELF3 expression levels than the Her2 subtype, revealing a tighter connection between ELF3 and BRCA1-associated breast cancers." (PMID 41498327, 2026). "In addition, there are likely other DEGs in our BRCA1-deficient RNA-seq that play important roles in the progression of BRCA1-associated breast cancer, and these genes also have potential research value." (PMID 41498327, 2026). "The BRCA-P trial is an ongoing randomized study evaluating whether denosumab can reduce the risk of breast cancer in healthy BRCA1 germline mutation carriers." (PMID 41488281, 2026). "The strongest evidence favoring platinum-based/FOLFIRINOX strategies involves homologous recombination repair deficiency (HRD), especially alterations in germline breast cancer gene 1/2 (BRCA1/2) or partner and localizer of BRCA2 (PALB2), as well as broader genomic scar signatures." (PMID 42193022, 2026). "Those that have other non‐BRCA1/2 PVs may need further genetic testing or risk models to assess their probability of developing breast cancer." (PMID 41568159, 2026). "CONCLUSION: A rare de novo BRCA1 variant was identified in a young breast cancer patient." (PMID 41814353, 2026). "ELF3 is upregulated in BRCA1-associated breast cancers and is related to a worse prognosis." (PMID 41498327, 2026).
breast cancer (continued). "Trials evaluating the benefit of PARP-inhibitors in breast cancer patients with mutations in HR-pathway genes other than BRCA1/2 have only included a very limited number of BRIP1-mutation patients and have not been able to confirm a PARP-inhibitor benefit for BRIP1-carriers." (PMID 40988318, 2025). "In contrast, BRCA1 carriers are known to have a higher risk of contralateral breast cancer, which may increase the likelihood of recommending prophylactic mastectomy." (PMID 41302125, 2025). "Breast cancer is the most common malignancy among women worldwide, with 5–10% of cases attributable to hereditary predisposition, primarily due to pathogenic variants in the BRCA1 and BRCA2 genes." (PMID 41302125, 2025). "Next, we investigated whether the pregnancy could affect mammary tumor development in mice carrying the Brca1 mutation." (PMID 40157910, 2025). "In breast cancer, besides mutational profile, BRCA1 and 2 expression levels modified by any other mechanism are proven to be important for patient survival and disease prognosis, which is why low BRCA expression is starting to take more importance in patient management." (PMID 41373491, 2025). "Deficiency in BRCA1 in human breast cancer cell lines increases sensitivity to UV-C irradiation." (PMID 40723324, 2025). "Therefore, more data is needed to support our findings that BRCA1/2 incidence is lower in NB, giving way to higher frequencies of variants in other breast cancer genes such as ATM." (PMID 39907309, 2025). "However, the other genes, beyond BRCA1/2, which are supposed to be the cause of hereditary breast cancer have a much higher frequency of variants of uncertain significance (VUS)." (PMID 39996890, 2025). "In the context of BRCA1-related functions, these genes may contribute to the complex regulatory network associated with the BRCA1 pathway, influencing cellular responses, immune modulation, and therapeutic resistance in breast cancer." (PMID 40870889, 2025). "The SNPs of BRCA1 rs1799949 are nonsense mutations and are associated with breast cancer in Taiwan." (PMID 40361383, 2025). "BRCA1 is a tumor suppressor gene linked to the inherited susceptibility to breast cancer." (PMID 40573960, 2025). "However, our findings align with other studies showing that men with BRCA1/2 variants, despite being less frequently affected by breast cancer themselves, experience considerable worry for their female family members." (PMID 40390061, 2025). "Notably, 3.5 – 10.9% of hereditary breast cancer cases involve non-BRCA1/2 gene variants, which are also significantly associated with breast cancer susceptibility." (PMID 40800071, 2025). "In a female patient, diagnosed with breast cancer at the age of 62, the structural variant (SV) analysis algorithm identified a heterozygous insertion of an unknown motif in exon 16 of the BRCA1 gene." (PMID 41375073, 2025). "However, 5–10% of cases are inheritable and are associated with germline mutations in several cancer predisposition genes, mainly breast cancer-associated gene-1 and 2 (BRCA1/2)." (PMID 40157910, 2025). "Specifically, for BRCA1 mutation carriers, the cumulative risk of ovarian cancer by age 80 is 44% (95% CI, 36%-53%), and the cumulative risk of contralateral breast cancer 20 years after a breast cancer diagnosis is 40% (95% CI, 35%-45%)." (PMID 40065879, 2025). "BRCA1 is an important breast cancer susceptibility gene first identified in 1994." (PMID 39392573, 2025). "Conversely, in breast cancer patients with somatic BRCA1/2 mutations, APOBEC-mediated mutations may be passenger mutations, particularly when the BRCA1/2 mutations have limited functional impact." (PMID 40356722, 2025). "Basal-like breast cancer, often triple-negative, is frequently associated with high genomic instability and homologous recombination (HR) deficiency, which typically results from BRCA1 mutations or dysfunctions." (PMID 41323735, 2025).
breast cancer (continued). "Mutations in the BRCA1 gene are a common cause of hereditary ovarian and breast cancer." (PMID 40519304, 2025). "The main risk factors for breast cancer are age, a personal history of breast pathology, a family history of breast cancer including genetic predisposition (mainly BRCA1 or 2), and a history of high-dose thoracic radiotherapy (as part of treatment for Hodgkin’s lymphoma, for example)." (PMID 40142718, 2025). "Given the high incidence of tumors in BRCA1 mutant carriers, the National Comprehensive Cancer Network (NCCN) recommends that women with BRCA1 mutations undergo regular breast screening and consider risk-reducing surgery to lower the incidence of breast cancer." (PMID 41208884, 2025). "The risk of breast cancer in BRCA1 PV carriers may vary by age, family history, and reproductive history." (PMID 41440233, 2025). "Furthermore, scRNA‐seq revealed the cellular origins and evolutionary patterns of breast cancer in BRCA1 mutation carriers, identifying potential therapeutic targets for patients with BRCA1 mutations." (PMID 40062730, 2025). "Additionally, BRCA1-deficient mouse mammary tumors that became resistant to Olaparib after initial response were found to have lost 53BP1 and partially recovered HR." (PMID 41243969, 2025). "A few years later, in 2018, olaparib became the first PARP inhibitor approved by the FDA for the second-line treatment of breast cancer patients with BRCA1/2 germline mutations who have previously undergone chemotherapy or hormone therapy if hormone receptor-positive." (PMID 40003864, 2025). "This study aimed to evaluate the effects of oral DHA supplementation on plasma resolvin D1 and D2 levels in breast cancer patients and in controls, and by stratifying the patients by disease presentation (sporadic, familial, BRCA1/2 mutated) and immunohistochemical characteristics." (PMID 40427191, 2025). "In contrast, the CARRIERS (Cancer Risk Estimates Related to Susceptibility) study, which included individuals both with and without a strong family history of breast or ovarian cancer, reported breast cancer risk estimates of less than 50% by age 70 for carriers of P/LP variants in BRCA1 and BRCA2." (PMID 39858629, 2025). "Consequently, individuals with a BRCA1 gene mutation will have an increased likelihood of developing breast cancer and are prone to manifesting the disease at a younger age." (PMID 40283136, 2025). "To evaluate whether enhancement of the immune response can suppress BRCA1-associated breast cancer, we treated tumor-bearing Brca1co/coMMTV-Cre mice with anti-mPD-1 mAb or isotype antibody as a control." (PMID 41208884, 2025). "In this global study of young BRCA carriers with breast cancer, distinct patient, tumor, and treatment characteristics and a different pattern and risk of survival events over time were observed between patients carrying germline BRCA1 and BRCA2 PVs." (PMID 39993249, 2025). "•Factors impacting breast cancer prognosis include patient age, overall health, tumor stage, tumor size, lymph node involvement, histologic grade, and the presence of certain gene mutations (e.g., BRCA1 and BRCA2)." (PMID 40831739, 2025). "Similarly, olaparib, a PARP inhibitor, was not approved as a monotherapy for mCRPC following a positive Breast Cancer Gene 1 and Breast Cancer Gene 2 (BRCA1/2) mutation analysis, necessitating tumor board recommendations to facilitate cost coverage." (PMID 40047924, 2025).
breast cancer (continued). "Additionally, about 11% to 19% of patients diagnosed with TNBC have either germline or somatic BRCA1 mutations, highlighting the genetic link between BRCA1 alterations and this aggressive breast cancer subtype." (PMID 39858010, 2025). "Furthermore, PRS313 has demonstrated potential in refining contralateral breast cancer risk predictions for BRCA1/2 PV carriers." (PMID 40296163, 2025). "Furthermore, the (ER)-negative PRS 313(which uses the same variants but with weights adapted to provide better prediction for ER-negative disease) was associated with breast cancer risk (HR = 1.29, 95% CI [1.25–1.33]) among BRCA1 PV carriers." (PMID 40296163, 2025). "According to the guidelines of the American Society of Clinical Oncology (ASCO) and the European Society of Medical Oncology (ESMO), the most significant genetic factor in the diagnosis and treatment of breast cancer is the mutation status of the BRCA1 and BRCA2 genes." (PMID 40724954, 2025). "Our clinical genetic testing, in particular, benefits from the presence of five of the most common mutations of BRCA1 (c.181T>G, c.4035del, c.5266dup, c.3700_3704del, c.68_69del and c.5251C>T), which constitute about 77% of all BRCA1/2 mutations detected in Polish women with breast cancer." (PMID 40002208, 2025). "Consequently, the frequency of pathogenic variants of BRCA1/2 in this study was also high, (n = 5; 13.9%), compared with the commonly reported frequency of BRCA1/2 variants in breast cancer, which is 4%–5%." (PMID 39831988, 2025). "For example, for BRCA1, there is an overall relative risk of 10-fold for breast cancer." (PMID 40350252, 2025). "We found that 16.8% (95% CI, 11.1%-23.9%) of participants with MpBC who underwent germline testing had PGVs in breast cancer susceptibility genes, with PGVs seen across MpBC subtypes and with most PGVs occurring in BRCA1 (11.9% variant prevalence) and BRCA2 (3.5%)." (PMID 39964682, 2025). "The significant prevalence of breast cancers among BRCA1 mutation carrier women may be explained by the unique requirement of the female breast for balanced liganded and unliganded ER activation." (PMID 41514592, 2025). "These mechanistic insights align with clinical strategies for TNBC that integrate DNA damaging agents and immunotherapy and validate this model as an optimal in vivo platform for preclinical evaluation of novel treatment modalities for BRCA1‐associated breast cancer." (PMID 41208884, 2025). "We evaluated whether the specific type of mutation or the location of the mutation on the gene impacts the risk of developing breast cancer among 3677 BRCA1 carriers." (PMID 41440233, 2025). "The highest risk of breast cancer is determined for carriers of BRCA1 and BRCA2 mutations." (PMID 40724954, 2025). "Interestingly, BRCA1 PV carriers also exhibited a higher risk of developing contralateral breast cancer and ovarian cancer after an initial breast cancer diagnosis." (PMID 40422528, 2025). "Notably, TRα2 overexpression correlates with improved survival outcomes in patients with breast cancer and is particularly upregulated in BRCA1-associated breast cancers, serving as a positive prognostic marker for both 5-year and overall survival." (PMID 40567613, 2025). "Similarly, extensive investigations in breast cancer have demonstrated that alterations within BRCA1 and BRCA2 not only modulate cancer susceptibility but also significantly influence survival trajectories." (PMID 40833230, 2025). "HIF-1 alpha was found to be more frequently overexpressed in BRCA1-mutated breast cancers." (PMID 40863152, 2025). "The breast cancer susceptibility genes (BRCA) are tumor suppressor genes including BRCA1 and BRCA2." (PMID 40182045, 2025).
breast cancer (continued). "In patients with homologous recombination deficiency (HRD) or somatic/germline BRCA1/2 (Breast Cancer 1/ Breast Cancer 2) mutations, maintenance treatment after response to platinum-based chemotherapy consists of Poly-ADP-Ribose-Polymerase-inhibitors (PARPi) olaparib in combination with bevacizumab." (PMID 39680144, 2025). "However, the overall impact of BRCA1/2 mutations on survival outcomes in breast cancer patients remains an area of ongoing research." (PMID 40405286, 2025). "It appears that drug susceptibility in triple-negative BRCA1-proficient breast cancer cells is linked to the reduced expression of the BRCA1 protein in repairing DSBs after ruthenium exposure; meanwhile, olaparib targets the PARP enzyme, which leads to cancer cell death via synthetic lethality." (PMID 41155174, 2025). "In addition, the analyses reported reduced breast cancer-specific mortality in breast cancer-affected women carrying BRCA1/BRCA2 P/LP variants combined (RR 0.26; 95% CI 0.18–0.39)." (PMID 39858629, 2025). "Notably, 27% of aggressive molecular biological subtypes of breast cancer (Luminal B and triple-negative) were identified at stage I in Group A1, and the most common BRCA1 variant was c.5266dupC (rs80357906), accounting for 64.3% of such patients." (PMID 40834323, 2025). "About 5–10% of breast cancers are inherited with approximately 30% of the inherited breast cancers were attributed to germline mutations in high penetrance breast cancer susceptibility genes, Breast Cancer susceptibility genes type 1 (BRCA1) and Breast Cancer susceptibility gene type 2 (BRCA2)." (PMID 40531958, 2025). "In the development of breast cancer and ovarian cancer, lifestyle and environmental factors seem to play a statistically significant role in the presence of genetic predisposition associated with BRCA1 and BRCA2 gene mutations." (PMID 41092066, 2025). "According to Polish guidelines, a panel of these five founder mutations of BRCA1 is used as an initial screening tool for all patients with breast cancer and/or ovarian cancer, and healthy individuals with a family history of at least breast and/or ovarian cancer." (PMID 40002208, 2025). "Therefore, risk-reducing salpingo-oophorectomy (RRSO) is recommended for patients with breast cancer who carry BRCA1/2 pathogenic variants." (PMID 40070605, 2025). "Importantly, knowledge of BRCA status before breast cancer diagnosis was associated with a trend toward improved DFS (in BRCA1 carriers only) and significantly better unadjusted BCSS and OS (in both BRCA1 and BRCA2 carriers)." (PMID 39993249, 2025). "A main concern about the surgical treatment of BRCA1/BRCA2 mutations breast cancers is whether breast conserving surgery (BCS) combined with radiotherapy is equivalent to radical mastectomy or not." (PMID 41303129, 2025). "Moreover, and in agreement with preceding data, loss of SETD1A also restored Olaparib-induced RAD51 foci formation and thus HR activity in both BRCA1-mutated ovarian and breast cancer cell lines and in ATM-mutated lung cancer cells." (PMID 39994444, 2025). "Additionally, BRCA1/2-deficient breast cancers have a higher expression of immunosuppressive molecules compared with BRCA1-WT breast cancers in WSI and TCGA cohorts, including CTLA-4, IDO1, and LAG3." (PMID 40830526, 2025). "BARD1 and BRCA1/2 mutation carriers had a strong family history of breast cancer." (PMID 40805222, 2025). "This instability drives the aggressive nature and carcinogenesis of BRCA1-mutated breast cancer." (PMID 39997609, 2025).